OR1K1 (olfactory receptor family 1 subfamily K member 1)
Description:
Odorant receptor.
Synonyms: hg99; MNAB
Tractability: Antibody: UniProt places it where antibodies can reach, with medium confidence; UniProt predicts a signal peptide or a membrane-spanning region; its Gene Ontology location is reachable by antibodies, with medium confidence.
Gene: Protein-coding gene on chromosome 9 (122,800,123 to 122,801,073, forward strand). Ensembl gene ENSG00000165204.
Subcellular location: Cell membrane
Pathways (Reactome):
Sensory Perception: Expression and translocation of olfactory receptors
Gene Ontology:
Molecular function: odorant binding; olfactory receptor activity; G protein-coupled receptor activity
Biological process: detection of chemical stimulus involved in sensory perception of smell; G protein-coupled receptor signaling pathway
Cellular component: membrane; plasma membrane
Genetic constraint (gnomAD): Loss-of-function variants: 1 observed, 1.27 expected, observed/expected ratio (o/e) 0.79, 90% interval 0.23 to 1.87. That is too few expected variants to judge how well the gene tolerates losing a copy. Missense variants: 409 observed, 422.2 expected, observed/expected ratio (o/e) 0.97, 90% interval 0.89 to 1.05. Synonymous variants: 168 observed, 186.61 expected, observed/expected ratio (o/e) 0.9, 90% interval 0.79 to 1.02.
Homologues: Orthologues: chimpanzee OR1K1 (96% identical), dog OR1K1 (89% identical), pig OR1K1 (86% identical), macaque OR1K1 (81% identical). Paralogues in human: OR1F1 (54% identical), OR1L4 (53% identical), OR1L6 (52% identical), OR1E1 (51% identical), OR1A1 (50% identical), OR1E2 (50% identical), OR1J4 (50% identical), OR1M1 (50% identical), OR1C1 (49% identical), OR1J2 (48% identical), OR1L1 (48% identical), OR1L3 (48% identical), and 116 more.